CHEK2 (checkpoint kinase 2)
Diseases named in the same sentence as CHEK2 in open-access papers (continued):
Sharing a sentence is not in itself a finding about the gene and the disease.
cancer (continued). "Recommended guidelines for early detection and cancer risk reduction in women with PVs in moderate-penetrance risk genes increasing lifetime cumulative risk over 20%, including PALB2, ATM, and CHEK2, are starting to become available." (PMID 38339330, 2024). "It was recently demonstrated that PRS created meaningful risk gradients among female carriers of PVs in cancer-predisposing genes other than BRCA, including ATM, CHEK2, PALB2, BARD1, BRIP1, CDH1, and NF1." (PMID 38339330, 2024). "Using the currently available data, we aim to study cancer risks in our heterozygous and homozygous CHEK2 c.1100delC families." (PMID 39384226, 2024). "Over 90% of clinical germline CHEK2 missense variants are classified as variants of uncertain significance, complicating diagnosis of CHK2-dependent cancer." (PMID 39642869, 2024). "Three main CHEK2 PVs (p.Thr476Met, p.Arg137Gln, and c.592+3A>T) were more highly present in the study cohort than the non-cancer group, and geneticists should carefully consider these while interpreting variations for patients of Turkish origin." (PMID 39594831, 2024). "Potential germline pathogenic CHEK2 variants were found in 3.5% (18/516) of AGCT patients, a rate that was 2.8‐fold higher than Genome Aggregation Database non‐cancer subjects (95% CI 1.8–4.6, p < 0.001)." (PMID 38898688, 2024). "These cancer-associated variants all abolish the normal activity of the CHEK2-encoded protein, a protein kinase called Chk2." (PMID 39146382, 2024). "Most CHEK2-deficient cancers presented with the clock-like mutational signatures SBS1 (5/16 cancers; 31%) and/or SBS5 (14/16 cancers; 88%)." (PMID 38848470, 2024). "In the non‐cancer cohort, 25/492 (5%) participants carried 17 unique P/LP variants in ATM, BRCA2, BRIP1, CHEK2, MUTYH, NBN, and PMS2 genes." (PMID 38308423, 2024). "Ideally, this should be expanded to more cancer types occurring in individuals who have biallelic CHEK2 gPVs and to more cancers per type." (PMID 38848470, 2024). "Here we consider rare variants in two genes, Checkpoint Kinase 2 (CHEK2) and Ataxia-Telangiectasia Mutated (ATM), that are included on many cancer gene panels." (PMID 39209703, 2024). "In this paper, we examine data from a large cohort study to derive relative and absolute risks for all cancer types, for carriers of PTVs and rMSVs in CHEK2 and ATM." (PMID 39209703, 2024). "PARPi activity was also demonstrated for BRCAwt cancers due to mutations in genes critical for DNA repair (e.g., ATM, BARD1, BRIP1, CHEK2, NBN, PALB2, RAD51C, and RAD51D)." (PMID 36910637, 2023). "Overall, 15 patients out of 521 (2.9%) showed PVs and LPVs in five cancer-predisposing genes other than BRCA1/2 (PALB2, CHEK2, ATM, RAD51C, and RAD51D)." (PMID 37628581, 2023). "Recurrent P/LP variants were identified in individuals diagnosed with cancer from distinct families, in the following cancer genes: BRCA1 (n = 3), LZTR1 (n = 3), HNF1A (n = 2), CHEK2 (n = 2), MITF (n = 2), and CHD4 (n = 2)." (PMID 37377903, 2023). "For SAS cancer cells, arecoline leads to cell death, apoptosis, and cell cycle arrest by stimulating checkpoint kinase 1 (Chk1) and checkpoint kinase 2 (Chk2) phosphorylation." (PMID 38139811, 2023). "To provide efficacious anti-cancer treatment and chemoprevention for these women, we need to identify the Achilles’ heel for CHEK2-driven tumorigenesis." (PMID 37161532, 2023).
cancer (continued). "Analyses have revealed that CHEK2 is a multisite cancer gene with different penetrance, including prostate, kidney, breast, and thyroid cancers." (PMID 38136334, 2023). "Specific inhibition of CHEK2 during cancer treatment is a potential strategy to preserve ovarian function in cancer patients." (PMID 37862420, 2023). "The median age for cancer diagnosis across the BRCA1/2 mutation carriers was 46 years, in the CHEK2 group it was 42.5 years, 44.8 years for ATM, 48.6 years for PALB2, 44 years for MUTYH, and 45.6 years for BLM." (PMID 38201513, 2023). "We also review the current body of data regarding CHEK2 germline alterations in the pediatric cancer population and future challenges with studies on these alterations." (PMID 36980535, 2023). "The interaction between PTBP1 and CHEK2 pre-mRNA results in the upregulation of a CHEK2 isoform containing exon 8 and enhances the cell survival of cancer cells." (PMID 37215575, 2023). "Our study is the largest and the most comprehensive functional analysis of real-world germline CHEK2 missense VUS found in patients with various cancer diagnoses and in controls." (PMID 37449874, 2023). "Regarding the mutation hotspots and mutation types in cancer, most of the truncating mutations of ATM, ATR, CHEK1, and CHEK2 are considered to be, at least, likely pathogenic." (PMID 37373360, 2023). "These conversations and recommendations regarding testing and cancer screening for CHEK2 alterations will likely continue to evolve over time as we better understand their contribution to adult and pediatric cancers." (PMID 36980535, 2023). "Checkpoint kinase 2 (CHEK2) plays a crucial role in responding to DNA damage and is linked to diverse cancer types." (PMID 38081888, 2023). "Here, we analyzed CHEK2 in 129 TGCT cases unselected for age of onset, histology, clinical outcome, and family history of any cancer, and the frequency of identified variants was compared to findings in 27,173 ancestry-matched cancer-free men." (PMID 38002677, 2023). "It additionally binds and modulates checkpoint kinase-2, a key cell cycle regulatory protein in normal and cancer cells." (PMID 37630263, 2023). "Herein, we report on six pediatric patients diagnosed with malignancy or hematologic disease and subsequently observed to harbor germline CHEK2 alterations." (PMID 36980535, 2023). "We observed that almost all tumors, including ccRCC, showed elevated CHEK2 expression compared to non-carcinoma samples." (PMID 38081888, 2023). "The results are the following distribution of cancer-associated mutations in genes: BRCA1 (31.4%), BRCA2 (12.2%), CHEK2 (10.5%) and other HCPS genes (45.9%), which is similar to our data." (PMID 36290365, 2022). "Core (BRCA1/2, PALB2), and any HRR mutations (BRCA1/2, PALB2, CHEK2, FANCA, ATM) occurred in 13 (10.3%) and 22 (17.5%) cancers, respectively." (PMID 36124727, 2022). "Studies on genetic predisposition to cancer diseases revealed the existence of a number of founder alleles and recurrent mutations in several genes, including BRCA1, CHEK2, and PALB2 genes." (PMID 35313928, 2022). "Checkpoint kinase 2 (CHEK2) is a gene involved in DNA damage repair, and its mutation was associated with many cancers including those of the breast, colon, kidney, thyroid, and prostate." (PMID 36009531, 2022).
cancer (continued). "A second germline variant was found in PALB2, CHEK2, ATM, and NBN, and they presented an additional cancer at the ages of 37, 57, 52, and 58, respectively." (PMID 36003761, 2022). "For each patient, we also showed the risk in the well-known high-penetrance cancer risk alleles BRCA1 and BRCA2 with respect to other moderate-penetrance alleles including PALB2, CHEK2, ATM, BARD1, RAD51D, RAD51C and BRIP1." (PMID 35886069, 2022). "PV were detected in 13 cancer predisposition genes including ATM (n=4), BLM (n=1), BRCA1 (n=1), BRCA2 (n=7), BRIP1 (n=1), CDKN2A (n=1), CHEK2 (n=9), FANCC (n=1), MUTYH (n=10), NBN (n=1), PALB2 (n=1), RAD51D (n=1) and STK11 (n=1)." (PMID 36091166, 2022). "Further cancer risks that are associated with these MBCG are pancreatic cancer for ATM, CHECK2, and PALB2, and colon and prostate cancer for CHEK2." (PMID 35329227, 2022). "Concordantly, analysis of clinical cancer datasets revealed that deletion of JAK2 is associated with increased genome alteration; and alteration in CHEK2 and JAK2 is linked to preferential deletion or amplification of cancer-related genes." (PMID 35851582, 2022). "Disrupting the DNA repair system, which includes the CHEK2 gene, leads to genomic instability, which is responsible for tumor progression and transformation of normal cells into cancer cells." (PMID 33530461, 2021). "We conducted a similar multivariate regression analysis for somatic mutations, and identified 24 significant associations in five (i.e., BRCA1, BRCA2, ATM, ATR, CHEK2) genes and higher HRD (FDR < 0.05) across cancer types." (PMID 34572800, 2021). "Among the conserved DNA-damage activated kinases identified so far, the CHEK2 plays a central role in implementing many aspects of the checkpoint response, related to the occurrence of various cancers." (PMID 34630562, 2021). "Hence, CHEK2 is speculated to be a low-penetrance, multiorgan cancer susceptibility gene." (PMID 34630562, 2021). "Thus, germline mutation in CHEK2 may cause genomic instability and lead to cancer predisposition." (PMID 34549727, 2021). "In a study utilizing multiple-gene panel testing, 23% of breast malignancies in young women were related to germline mutations in known cancer predisposition genes such as BRCA1/2, CHEK2, ATM and PALB2." (PMID 34011307, 2021). "A small, but unique group of 16 non-FAP mesenteric desmoid was found to harbor genetic alterations in cancer associated genes other than APC, including CHEK2, BLM, ERCC5, MSH6, and PALB2." (PMID 34359575, 2021). "In the present study, 35% of PABC patients tested carried pathogenic mutations in two known cancer predisposition genes (BRCA1 and CHEK2)." (PMID 34011307, 2021). "Compared to the frequency of mutations in cancer-free controls from our previous studies, we observed statistically significant associations for PALB2 (OR = 11.66 p < 0.001) and for CHEK2 truncating mutations (OR = 2.93; p = 0.02)." (PMID 34461861, 2021). "Biallelic CHEK2 PV carriers were significantly more likely to be affected with at least one primary cancer as compared to monoallelic PV carriers (90.3% vs. 50.0%, p < 0.0001)." (PMID 31993860, 2020). "The converse comparison of unaffected monoallelic and biallelic CHEK2 PV carriers revealed that biallelic carriers were significantly less likely to be unaffected with cancer as compared to monoallelic carriers (p < 0.0001)." (PMID 31993860, 2020). "On average, biallelic carriers of CHEK2 PVs were diagnosed with breast and other cancers at younger ages than monoallelic carriers." (PMID 31993860, 2020). "When expanding our investigation of other cancer predisposition genes besides ALK and PHOX2B, we detect rare variants such as a nonsense mutation in BARD1 as well as missense variants in CHEK2, BRCA2, and WRN." (PMID 33384420, 2020). "Germline variants in BARD1 and CHEK2 have indeed been shown to be enriched in NB patients, while BRCA2 has been shown to be enriched in pediatric cancer patients." (PMID 33384420, 2020).
cancer (continued). "In order to better assess the cancer risks in rare female carriers of biallelic CHEK2 PVs, we identified CHEK2 PV carriers in a large series of patients undergoing hereditary cancer panel testing." (PMID 31993860, 2020). "CHEK2 PV carriers were identified through commercial hereditary cancer panel testing (09/2013–07/2019)." (PMID 31993860, 2020). "This study compared the cancer phenotypes of women with biallelic PVs in CHEK2 to monoallelic carriers identified by hereditary cancer panel testing." (PMID 31993860, 2020). "Variants in CHEK2 and ATM can impact cancer surveillance and cancer screening, as well as prevention for blood relatives." (PMID 32881420, 2020). "Inhibition of endogenous Per1 expressionresulted in the abrogation of the ATM/Checkpoint kinase 2 (Chk2) checkpoint pathway and led to less DNA damage-induced apoptosis of cancer cells." (PMID 32437452, 2020). "Pathogenic variants were identified in CHEK2, MUTYH, and RAD51B in four cancer patients, which represented 8.3% of the cohort." (PMID 31780696, 2019). "In our analysis, we found that seven out of 10 pedigrees had potential co-segregated pathogenic variants in known cancer-associated genes, including CHEK2, ATM, MRE11, and CTR9, and some other cancer-associated genes, such as IGF2R and CHRNA3." (PMID 31214250, 2019). "Instead, most were in moderate-penetrance genes that confer a two- to four-fold increase in cancer risk (eg, ATM and CHEK2) as well as low-penetrance mutations (eg, monoallelic MUTYH and APC I1307K)." (PMID 34322651, 2019). "The underlying principles and management frameworks are also applicable to other cancer predisposition genes, particularly the more common, lower penetrance CPGs such as ATM and CHEK2, which will often be incidental findings." (PMID 31360904, 2019). "Mouse knockouts of RAD50 are embryonic lethal, and, like CHEK2, RAD50 mutations are associated with cancer risk." (PMID 30305041, 2018). "Overall, a candidate disease-causing mutation in a cancer predisposing gene was identified in 18 patients (14.9%), with ATM and CHEK2 representing 61.1% of the cases." (PMID 29659569, 2018). "W-2b conferred a robust increase in phosphorylation of mammalian checkpoint kinase-2 (Chk2) in cancer cells in a dose-dependent manner." (PMID 29062040, 2017). "Although homozygous inactivation of CHEK2 in mice led to cancers in multiple organs, accumulation of additional human cases is needed to establish its pathogenic role in humans." (PMID 27900359, 2016). "The CHEK2 decrease suggests a role of cancer cells in suppressing CHEK2 expression in fibroblast cells present in their vicinity, either directly or indirectly." (PMID 27484185, 2016). "The rarity of mutations in PALB2, CHEK2 and ATM make it difficult to estimate precisely associated cancer risks." (PMID 27595995, 2016). "Collectively, these data identify SOD1 as a novel candidate drug target in BLM and CHEK2 cancer contexts, and further suggest that 2ME2, ATTM and LCS-1 are lead therapeutic compounds warranting further pre-clinical study." (PMID 26318585, 2015).
cancer (continued). "As noted in the CHEK2 and NBN cases above, outside of specific founder mutations, cancer-related risks for these genes remain ambiguous." (PMID 26484312, 2015). "This supposition is supported by the fact that (excluding hyper-mutated tumors) there are no occurrences of tumors with mutations in both RAD17 and either CHEK1, CHEK2 and WEE1 across all cancer types in TCGA." (PMID 26437225, 2015). "In cases with wild-type KRAS, BRAF and PIK3CA a number of cancer-associated genes representing potential drivers were identified (for example, STK11, GNAS, CHEK2 and RB1)." (PMID 25855536, 2015). "(-)-Epicatechin in combination with ionizing radiation stimulated Chk2 (checkpoint kinase 2) phosphorylation, p21 expression, and increased apoptosis, in cancer cells." (PMID 24516636, 2014). "While most cancers in the eight CHEK2 families were later onset, seven of them had at least one individual with a cancer diagnosed before the age of 50." (PMID 24506336, 2014). "After removing eight patients with CHEK2 mutations and 11 MUTYH heterozygotes, the percentage of patients with ‘actionable’ mutations that would clearly alter cancer screening recommendations per national guidelines decreased to 7.2%." (PMID 24506336, 2014). "Despite the fact that we included a total of 5953 cancer patients, there were only 533 CHEK2-positive cases and 431 affected relatives." (PMID 19401704, 2009). "Ours is the only large single-centre study of unselected cancer patients originating in a well-defined, ethnically homogeneous group from one country to address the genetic epidemiology of CHEK2." (PMID 19401704, 2009). "Although these pathways have been studied primarily in cancer cell lines, a number of mouse models of CHEK2 inactivation have provided some insight into the physiologically relevant pathways." (PMID 18797466, 2008). "Since 1100delC mutation has been reported in Li–Fraumeni syndrome and was previously called a mutation hot spot (CHEK2 [MIM 604373]), we looked other cancers in these four 1100delC-positive families." (PMID 14612911, 2003). "The broader gene analysis was driven by the possibility of misclassified primary tumours and increasing evidence that genes associated with other cancers (e.g., BRCA1, BRCA2, CHEK2) may also influence CRC risk through shared pathways." (PMID 40627234, 2025). "The PGV rate was largely contributed to by BRCA2 (1.7%), ATM (1.3%), CHEK2 (1.1%) and BRCA1 (0.5%) and PGVs in these genes were found at significantly higher rates in the high risk localized and advanced PCa cohort compared to cancer-free males." (PMID 40832411, 2025). "In this cohort study, biallelic CHEK2 LR variants did not appear to have a higher cancer penetrance than was found among individuals with a single LR variant." (PMID 39745704, 2025). "Furthermore, it showed that only patients with FAT1 variants had CRC, and most patients harboured variants in genes such as CHEK2, ERBB2, and KIT in most of the cancers." (PMID 40627234, 2025). "It has been suggested that genome alterations due to lowered or loss of CHEK2 and JAK2 expression may exacerbate cancer progression and predict poor patient survival." (PMID 40177144, 2025). "The CHEK2 R523H variant in these cases is favored to be of germline origin or non-specific mutations and probably not related to underlying malignancy in non-cancer cases." (PMID 40282516, 2025).